NUF2 (NUF2 component of NDC80 kinetochore complex)
Diseases named in the same sentence as NUF2 in open-access papers (continued):
Sharing a sentence is not in itself a finding about the gene and the disease.
pancreatic cancer (13 papers, 2017 to 2023). "According to previous reports, silencing Nuf2 by RNA interference can inhibit the proliferation of pancreatic cancer cells and cause cell cycle arrest in the G0/G1 phase by inhibiting Cyclin B1, CDC2, and Cdc25A." (PMID 35393397, 2022). "In stomach, ovarian and pancreatic cancer cell lines, gene knockout of NUF2 remarkably delays cell growth and increases cell apoptosis." (PMID 37138262, 2023). "One study reported that knockdown of NUF2 suppressed pancreatic cancer proliferation in vitro and in vivo." (PMID 29190974, 2017). "Down regulation of NUF2 in pancreatic cancer cell lines inhibited tumor growth and enhanced apoptosis whereas upregulation of NUF2 in colon cancer cells promoted tumorigenicity." (PMID 28122328, 2017). "Previous study indicated that the downregulation of NUF2 could inhibit the growth of pancreatic cancer." (PMID 31182966, 2019). "In addition, NUF2 overexpression is also related to poor prognosis in pancreatic cancer." (PMID 33403046, 2021). "In addition, NUF2 played a key role in pancreatic cancer profiles by regulating RNA lnc RNA 339813." (PMID 32565735, 2020). "The downregulation of NUF2, which regulates lncRNA AF339813, can inhibit the growth of pancreatic cancer." (PMID 37138262, 2023).
renal clear cell carcinoma (12 papers, 2021 to 2025). "A study has revealed that IGF2BP3 stabilized CDKN2B-AS1 to promote the progression of renal clear cell carcinoma via epigenetically activating NUF2 transcription." (PMID 37106446, 2023). "LncRNA CDKN2B-AS1 was stabilized by IGF2BP3, recruited CBP and SMYD3 and activated NUF2 transcription in renal clear cell carcinoma." (PMID 35676262, 2022). "NUF2 expression positively correlates with tumor-infiltrating CD8+ T cells and dendritic cells in clear renal cell carcinoma, while POLA2 has been identified as a positive biomarker for PD-L1 blockade response in mUC." (PMID 41357226, 2025). "For examples, in renal clear cell carcinoma, lncRNA CDKN2B-AS1 affected the malignancy through epigenetically activating NUF2 (NUF2 Component of NDC80 Kinetochore Complex) transcription." (PMID 34374638, 2021). "In renal clear cell carcinoma, CDKN2B-AS1 exerts its carcinogenic activity by recruiting CREB-binding protein and three epigenetic modification complexes containing SET and MYND domains to the promoter region of the Ndc80 mitochondrial complex (NUF2)." (PMID 34712660, 2021). "Similarly, CLIC5 expression was found to be lower than that of normal kidney tissues in renal clear cell carcinoma tissues extracted from our research center, while MXD3, NUF2, PABPC1L, and PLK1 were significantly higher in renal clear cell carcinoma tissues than in normal kidney tissues." (PMID 38546385, 2024).
prostate carcinoma (10 papers, 2017 to 2024). A carcinoma that arises from epithelial cells of the prostate gland. "In prostate cancer, Wong et.al found that knockdown NUF2 could significantly inhibit the growth of cancer cells." (PMID 36670423, 2023). "More importantly, the results from a phase I clinical trial of NUF2 peptide vaccination for castration-resistant prostate cancer showed that NUF2 peptide vaccine therapy could significantly maintain patient quality of life and extend survival." (PMID 35813477, 2022).
melanoma (8 papers, 2016 to 2025). A malignant, usually aggressive tumor composed of atypical, neoplastic melanocytes. "For instance, reduced expression of NUF2 can arrest melanoma cells in the G0/G1 phase, leading to cell cycle arrest." (PMID 40220284, 2025). "In melanoma tumors, NUF2 was highly expressed and significantly related to the poor prognosis of patients." (PMID 36670423, 2023). "Subsequently, we examined the regulatory effect of Prc1 and Nuf2 in human melanoma A375 cells, respectively." (PMID 35393397, 2022). "We believe that PRC1 and NUF2 can be used as targets for the treatment of melanoma." (PMID 35393397, 2022).
ovarian carcinoma (8 papers, 2017 to 2024). A malignant neoplasm originating from the surface ovarian epithelium. "NUF2 has been reported upregulated in various kinds of cancers including colorectal, gastric, breast, renal, and ovarian cancer." (PMID 39242581, 2024). "In ovarian cancer, NUF2 contributed to tumor initiation and development through PI3K-AKT and MAPK signaling axes mediated by ERBB3." (PMID 39242581, 2024). "Consistent with our results, one report also showed that NUF2 mRNA expression levels were significantly elevated in ovarian carcinoma tissues when compared with those in normal ovarian tissues." (PMID 36620547, 2022). "Previous studies suggest that depletion of NUF2 by specific siRNAs inhibit proliferation and induce apoptosis in non-small cell and ovarian cancer cells." (PMID 32565735, 2020). "NUF2 was also aberrantly overexpressed in ovarian carcinoma cell lines." (PMID 36620547, 2022). "Interestingly, NUF2 has been reported to be upregulated in ovarian cancer, and NUF2 knockdown by small interfering RNA (siRNA) inhibited cell viability and induced apoptosis." (PMID 36620547, 2022). "Eight genes (NUF2, GTSE1, DEPDC1, KIF18B, PBK, CEP55, HJURP, SKA1) were potential hub genes correlated to ovarian cancer progression." (PMID 35173547, 2022). "However, the role and precise mechanism of NUF2 in ovarian cancer progression remain unclear." (PMID 36620547, 2022). "However, the function and mechanism of NUF2 in epithelial ovarian cancer (EOC) remain unclear." (PMID 36620547, 2022). "Our further qRT-PCR showed that seven hub genes (BUB1, KIF2C, NUP43, NDC80, NUF2, CCNB2 and CENPN) were differentially expressed in platinum-resistant ovarian cancer cells." (PMID 34820170, 2021). "Depletion of NUF2 resulted in the inhibition of cell proliferation in non-small-cell carcinoma and ovarian cancer." (PMID 29190974, 2017).
glioma (7 papers, 2021 to 2023). A benign or malignant brain and spinal cord tumor that arises from glial cells (astrocytes, oligodendrocytes, ependymal cells). "Knockdown of NUF2 by small interfering RNA can inhibit tumour growth and induce apoptosis in human glioma cells." (PMID 33423377, 2021). "NUF2 has a potential role in glioma growth and TMZ resistance." (PMID 36588901, 2022). "Importantly, previous studies reported that AIFM3, LDHD, LYNX1, SCN2B or TMEM56 were all negatively corelated with glioma, and GINS1, KIFC1, NUF2, NUSAP1 or TPX2 were both positively related to glioma progression." (PMID 33277782, 2021).
lung adenocarcinoma (6 papers, 2020 to 2024). A carcinoma that arises from the lung and is characterized by the presence of malignant glandular epithelial cells. "CDCA6, also known as NUF2, promotes lung adenocarcinoma progression and is associated with a worse prognosis; these findings are consistent with our results." (PMID 38875380, 2024). "However, the functional roles of NUF2 and their underlying mechanisms in lung adenocarcinoma (LUAD) are largely unknown." (PMID 35814368, 2022). "Previous studies have analyzed NUF2 in lung adenocarcinoma using multiple omics methods, verifying that NUF2 mRNA is highly expressed in lung adenocarcinoma cell lines." (PMID 35814368, 2022). "Both human lung adenocarcinoma cell line (A549) and human lung squamous cell carcinoma cell line (H520) expressed significantly higher levels of NUF2 than the normal human bronchial epithelial cells (16HBE)." (PMID 34178642, 2021). "The expression of NUF2 in NSCLC, both lung adenocarcinoma (LUAD) and squamous lung cancer (LUSC), was significantly higher than that in normal tissues." (PMID 34178642, 2021). "Although NUF2 was over-expressed in several cancers, including lung adenocarcinoma, previous studies do not have analyzed NUF2 in lung adenocarcinoma from multi-omics aspects, and few study has analyzed this gene in squamous lung cancer." (PMID 34178642, 2021). "Previous evidence demonstrate that NUF2 plays as a prognostic biomarker and therapeutic target in hepatocellular carcinoma, breast cancer, and oral cancer, and NDC80 complex gene might be an early indicator of diagnosis and prognosis of lung adenocarcinoma." (PMID 34178642, 2021).
non-small cell lung carcinoma (5 papers, 2017 to 2025). A group of at least three distinct histological types of lung cancer, including non-small cell squamous cell carcinoma, adenocarcinoma, and large cell carcinoma. "In this analysis, NUF2 expression difference analysis in non-small cell lung cancer was evaluated by Oncomine, TIMER, GEO, and TCGA database." (PMID 34178642, 2021). "We also found that NUF2 gene was mainly amplified in non-small cell lung cancer." (PMID 34178642, 2021).
colon cancer (4 papers, 2017 to 2022). "NUF2 was certified to participate in the tumorigenicity of colon cancer cells." (PMID 31139013, 2019).
osteosarcoma (4 papers, 2019 to 2023). A usually aggressive malignant bone-forming mesenchymal neoplasm, predominantly affecting adolescents and young adults. "Besides, another study suggested that NUF2 might modulate cell proliferation via cell cycle control in Osteosarcoma Saos-2 cells, depletion-induced growth inhibition was associated with cell cycle arrest and apoptosis." (PMID 36670423, 2023).
pancreatic ductal adenocarcinoma (4 papers, 2021 to 2024). An infiltrating adenocarcinoma that arises from the epithelial cells of the pancreas. "Interestingly, NUF2 knockdown significantly inhibited pancreatic ductal adenocarcinoma cell migration and invasion." (PMID 36620547, 2022). "NUF2 is an oncogene regulated by CircFOXK2 in pancreatic ductal adenocarcinoma." (PMID 34699322, 2021). "CircFOXK2 promoted pancreatic ductal adenocarcinoma (PDAC) progression by interacting with YBX1 and hnRNPK proteins to upregulate the expression of NUF2 and PDXK oncogenes." (PMID 38890620, 2024).
head and neck cancer (3 papers, 2013 to 2024). A primary or metastatic malignant neoplasm affecting the head and neck. "We used this database to assess the dependence of a large panel of head and neck cancer cell lines on the expression of PLK1, AURKA, TPR, NUF2, NDC80, and TTK." (PMID 39392349, 2024).
cholangiocarcinoma (2 papers, 2023 to 2024). A carcinoma that arises from the intrahepatic biliary tree (intrahepatic cholangiocarcinoma) or from the junction, or adjacent to the junction, of the right and left hepatic ducts (hilar cholangiocarcinoma). "In addition, NUF2 can also facilitate the development of cholangiocarcinoma through p38/MAPK signaling by suppressing the p62 binding of TFR1 and affecting its autophagic degradation." (PMID 39242581, 2024). "We studied for the first time how NUF2 played a role in the autophagic degradation of TFR1 through p62, and uncovered the molecular mechanism of NUF2 promoting the progression of cholangiocarcinoma through TFR1." (PMID 37056930, 2023).
endometrial carcinoma (2 papers, 2020 to 2025). A malignant tumor arising from the epithelium that lines the cavity of the uterine body. "When it comes to uterine mixed endometrial carcinoma, another distinctive pattern emerged and the most were the high mRNA expression of almost all CDCA members except CDCA3/7, and the missense mutation of NUF2, CDCA2/3/5, CBX2, CDCA7/8." (PMID 32913454, 2020). "Additionally, among the genes closely associated with UBE2T expression, genes like DTL, NUF2, and MELK may also contribute to the progression of endometrial cancer." (PMID 39367897, 2025).
prostate adenocarcinoma (2 papers, 2023 to 2024). "Specifically, the levels of NDC80 were only decreased in acute myeloid leukemia (LAML) and prostate adenocarcinoma (PRAD), and NUF2 downregulation was only observed in LAML and testicular germ cell tumors (TGCT)." (PMID 39513104, 2024).
renal carcinoma (2 papers, 2024). A carcinoma arising from the epithelium of the renal parenchyma or the renal pelvis. "NUF2 acts as an oncogene in renal cancer by affecting the expression of HMGA2 by KDM2A-mediated H3K36me2 demethylation." (PMID 39242581, 2024). "The results of the TCGA-KIRC cohort showed that either in paired or unpaired renal cancer tissues, except for CLIC5, which was in a low expression state, the remaining four genes (MXD3, NUF2, PABPC1L, and PLK1) were in a high expression." (PMID 38546385, 2024).
serous adenocarcinoma (2 papers, 2012 to 2023). An adenocarcinoma that is characterized by the presence of papillary patterns and cellular budding. "Furthermore, two independent gene expression studies show that NDC80, NUF2 and PTN were significantly aberrantly overexpressed in serous adenocarcinomas." (PMID 23056589, 2012).
triple-negative breast carcinoma (2 papers, 2020 to 2023). An invasive breast carcinoma which is negative for expression of estrogen receptor (ER), progesterone receptor (PR), and human epidermal growth factor receptor 2 (HER2). "In this study, we have found that the expressions of NUF2 and FAM83D are associated with triple-negative breast cancer." (PMID 33005492, 2020). "In this study, we found that the expression level of NUF2 was higher in triple-negative breast cancer than in non-triple negative breast cancer and TNBC patients with higher NUF2 expression level had significantly reduced the recurrence-free survival." (PMID 33005492, 2020). "Next, we will further investigate whether the expression changes of NUF2/FAM83D in triple-negative breast cancer are caused by non-coding RNA." (PMID 33005492, 2020). "Finally, we validated the expression levels of NUF2, FAM83D and CENPH in 14 pairs of triple negative breast cancer paired tissues by using RT-qPCR." (PMID 33005492, 2020). "However, the expression level changes of NUF2 in triple-negative breast cancer have not yet been studied." (PMID 33005492, 2020).
asthma (1 paper, 2021). "Although ATG3 is a key central regulator in autophagy induction during aging, and NUF2 is closely associated with lung cell senescence, their specific role in asthma has rarely been studied." (PMID 34136532, 2021).
breast tumors (1 paper, 2019). "Just like the CST2, GJB2, UBE2T, NUF2 and ORC6 also showed the same high expression level in breast tumors." (PMID 31182966, 2019).
kidney cancer (1 paper, 2023). Primary or metastatic malignant neoplasm involving the kidney. "But the role of NUF2 in kidney cancer is poorly understood and further research is needed." (PMID 37138262, 2023).
leukemia (1 paper, 2021). A malignant (clonal) hematologic disorder, involving hematopoietic stem cells and characterized by the presence of primitive or atypical myeloid or lymphoid cells in the bone marrow and the blood. "However, there was no significant up-regulation of Nuf2 was found in leukemia, suggesting that it is necessary to distinguish the types of cancer when they were used as diagnostic genes." (PMID 33767990, 2021).
liver cirrhosis (1 paper, 2020). "Through the genome-wide expression microarray analysis of recurrent HCC, it is found that NUF2 complicated with liver cirrhosis can be used as a promising prognostic biomarker of early HCC recurrence." (PMID 33424998, 2020).
lymph node metastasis (1 paper, 2024). "NUF2 expression in primary tumors was correlated with lymph node metastasis and unfavorable outcomes in terms of poor recurrence-free and cancer-specific survival." (PMID 38472943, 2024). "In this study, NUF2 was highly expressed in NSCLC tissues, correlating significantly with lymph node metastasis and indicating a significant association with poor prognostic factors." (PMID 38472943, 2024). "NUF2 expression was higher in patients with lymph node metastasis (p = 0.034)." (PMID 38472943, 2024). "This suggests the possibility of detecting tumor micrometastasis by quantifying NUF2 expression in lymph nodes, which could be applied to intraoperative rapid diagnosis of lymph node metastasis while deciding on the indication for sublobar resection." (PMID 38472943, 2024).
prostate tumor (1 paper, 2022). "NUF2 is reported as one of tumor testis antigens that is secreted ectopically by cancers, and NUF2 levels are increased in prostate tumor tissues." (PMID 35600043, 2022).
psoriasis (1 paper, 2024). An autoimmune condition characterized by red, well-delineated plaques with silvery scales that are usually on the extensor surfaces and scalp. "The gene expression heatmap showed high expression of core genes (TOP2A, MELK) in psoriasis samples, while DEPDC1B, CCNA2, DLGAP5, NUF2, ASPM were lowly expressed in psoriasis samples." (PMID 38382096, 2024). "We found that core genes (TOP2A, MELK) were highly expressed in psoriasis samples and lowly expressed in normal tissue samples, while DEPDC1B, CCNA2, DLGAP5, NUF2, ASPM were lowly expressed in psoriasis samples." (PMID 38382096, 2024).
renal cell carcinoma (1 paper, 2022). "NEK2 and NUF2 have also well established roles in cell cycle regulation and cell proliferation and their overexpression was associated with a variety of cancer types including renal cell carcinoma." (PMID 35954157, 2022).
renal tumor (1 paper, 2020). "Next‐generation sequencing (NGS) analysis of the patient's renal tumor revealed the following heterozygous somatic alterations: FH (NM_000143 ‐ 1q43) intragenic deletion involving the loss of exon 1–2, KDM5C (NM_004187) exon 7 p.K289E (c.865A > G), and NUF2 (NM_031423) exon 8 p.S171C (c.512C > G)." (PMID 32463173, 2020).
Stroke (1 paper, 2012). Sudden impairment of blood flow to a part of the brain due to occlusion or rupture of an artery to the brain. "SMC4, NUF2 and ECT2 were augmented in the core and PI areas at 3 d after stroke." (PMID 23284893, 2012).
thyroid cancer (1 paper, 2024). "Collectively, these data support that NUF2 was upregulated in thyroid cancer and and its level is positively correlated with poor prognosis." (PMID 39242581, 2024). "In order to understand the function of NUF2 in thyroid cancer, we then evaluated the effects of NUF2 on ATC cell proliferation and apoptosis in vitro." (PMID 39242581, 2024). "The prognosis of patients with thyroid carcinoma was positively correlated with high NUF2 expression." (PMID 39242581, 2024). "Besides, NUF2 was overexpressed in ATC according to the thyroid-cancer cohort reported previously." (PMID 39242581, 2024).
uterine endometrioid carcinoma (1 paper, 2020). "In uterine endometrioid carcinoma, the prevalent high mRNA expression of almost all CDCAs except CDCA7, the amplification of NUF2, CDCA3/5, the deep deletion of CDCA2 and the missense mutation of CDCA7 presented the most common altered genetic events." (PMID 32913454, 2020).